SNHG29 (small nucleolar RNA host gene 29)
Synonyms: ACIL; MGC40157; C17orf45; C17orf76-AS1; FAM211A-AS1; LRRC75A-AS1; NCRNA00188; TSAP19
Gene: Long non-coding RNA gene on chromosome 17 (16,438,767 to 16,480,249, forward strand). Ensembl gene ENSG00000175061.
Gene Ontology:
Biological process: RNA processing
Cellular component: nucleolus
Diseases named in the same sentence as SNHG29 in open-access papers:
SNHG29 is named in the same sentence as 11 diseases in open-access papers, as found by Europe PMC text mining. Sharing a sentence is not in itself a finding about the gene and the disease. The quoted sentences say what the papers report.
osteosarcoma (2 papers, 2012 to 2019). A usually aggressive malignant bone-forming mesenchymal neoplasm, predominantly affecting adolescents and young adults. "SNHG29 (LRRC75A-AS1) has been reported to play an oncogenic role in osteosarcoma, the specific role of SNHG29 appealed to us a lot." (PMID 31889897, 2019). "Small nucleolar RNA host gene 29 (SNHG29) was also known as LRRC75A-AS1, which has been identified to regulate the development osteosarcoma." (PMID 31889897, 2019). "Emerging reports has claimed that SNHG29 (LRRC75A-AS1) was involved in several biological processes via modulation of signaling pathway, and served as an malignant facilitatorin osteosarcoma." (PMID 31889897, 2019).
colorectal cancer (1 paper, 2025). A primary or metastatic malignant neoplasm that affects the colon or rectum. "Another statin, simvastatin (in micromolar doses) also suppresses PD-L1 expression and enhances antitumor immunity in colorectal cancer by down-regulating long non-coding RNA (lncRNA) small nucleolar RNA host gene 29 (SNHG29)." (PMID 40270603, 2025).
glioblastoma (1 paper, 2019). The most malignant astrocytic tumor (WHO grade IV). "In conclusion, SNHG29 regulates miR-223-3p/CTNND1 axis to promote glioblastoma progression via Wnt/β-catenin signaling pathway, offering a potential therapeutic point for glioblastoma patients." (PMID 31889897, 2019). "All in all, SNHG29 regulates miR-223-3p/CTNND1 axis to promote glioblastoma progression via Wnt/β-catenin signaling pathway." (PMID 31889897, 2019). "Collectively, this study analyzed the association between ANHG29 expression and the overall survival of glioblastoma patients, indicating the prognostic potential of SNHG29 in glioblastoma patients." (PMID 31889897, 2019). "This research was the first time to investigate the function and mechanism of SNHG29 in glioblastoma and we verified that SNHG29 regulates miR-223-3p/CTNND1 axis to promote glioblastoma progression via Wnt/β-catenin signaling pathway." (PMID 31889897, 2019). "However, the specific role of SNHG29 in glioblastoma remains unknown." (PMID 31889897, 2019).
heart failure (1 paper, 2022). Inability of the heart to pump blood at an adequate rate to meet tissue metabolic requirements. "Other lncRNAs, including SNHG29 and PCAT19, have not been investigated in heart failure contexts, but they are known as potential regulators in cell signaling pathways." (PMID 35415316, 2022).
laryngeal carcinoma (1 paper, 2022). Carcinoma that arises from the laryngeal epithelium. "A recent study demonstrated that SNHG29 (small nucleolar RNA host gene 29) plays an important role in the invasion, migration, and epithelial-to-mesenchymal transition of laryngeal cancer, suggesting that SNHG29 is a potential therapeutic target." (PMID 35903713, 2022).
leishmaniasis (1 paper, 2024). Infectious disease that is transmitted through the bite of hematophagous female phlebotomine sand flies. "In the context of leishmaniasis, SNHG29, a member of the SNHG family, was determined as hub lncRNA targeting S100A8 mRNA in L. braziliensis skin infection." (PMID 39639867, 2024).
melanoma (1 paper, 2023). A malignant, usually aggressive tumor composed of atypical, neoplastic melanocytes. "The over-expressions of both NEAT1 and SNHG29 are all associated with poor survival in TCGA melanoma cohort." (PMID 36765063, 2023).
SNHG29 also shares sentences with these, for which no sentence is quoted: cancer (2 papers); glioma (1); prostate carcinoma (1); skin infection (1).